TNF (tumor necrosis factor)
Diseases named in the same sentence as TNF in open-access papers (continued):
Sharing a sentence is not in itself a finding about the gene and the disease.
infection (continued). "For example, when applying the risk calculator, a 65-year-old RA patient with low disease activity on prednisone 5 mg has a predicted serious infection risk of 2.4% with TNF inhibition." (PMID 32974356, 2020). "The production of TNF-α by macrophages when stimulated with INF-γ is associated with resistance to infection in mice." (PMID 32266161, 2020). "On the other hand, resistant C3H/He mice presented a lower repertory of cytokines mRNA expression when compared with susceptible C57BL/10 mice, basically producing TNF-α, collagen IV, and laminin early in infection." (PMID 32983013, 2020). "TNFα mRNA levels were significantly elevated after infection with the phosphodiesterase-deficient pneumococci, with comparable effects noted for all the mutant bacteria." (PMID 32300347, 2020). "TNFα makes a priming of astrocytes, enhancing their susceptibility to T. cruzi infection creating a cycle of infection and neuroinflammation because astrocytes are producers of TNFα in the spinal cord." (PMID 33574810, 2020). "Whereas, the risk of serious infections under anti-IL-17 therapy is comparable to that of TNF-blockers; anti-IL-12/23 therapy seems to carry a lower risk (HR = 0.59, 95% CI 0.39–0.90)." (PMID 33154972, 2020). "By day 14, the mean TNF-α concentrations in lung homogenates associated with the ST5 infections had declined from 3933.71 pg/g lung to 2802.36 pg/g lung (P < .001)." (PMID 32196550, 2020). "The results indicated that infection of KP caused a significant increase in the secretions of TNF-α and IL-6 in mouse serum." (PMID 32625244, 2020). "In contrast, mice with TNF deficiency in B cells controlled the infection similarly, compared with TNFf/f mice." (PMID 32742607, 2020). "Cytokines such as IL-6, IL-1β, IL-17 and TNF-a have been associated with exacerbation of the infection, with TNF-a, an important NO inducer, being particularly significant in mucosal leishmaniasis evolution." (PMID 32321156, 2020). "After infection with the pathogenic fungi, they found that the production of IL-1β, IL-6, IL-8, IL-12, TNF-α, CCL2, and CCL5 was significantly increased after the addition of moDCs." (PMID 32957440, 2020). "TNF-a as an important inflammatory factor that can act as an anti-infection pyrogenic factor that causes fever." (PMID 33102586, 2020). "In an epithelial mono-cell culture (NCI-H441 cells) bacterial infection caused a much lower increase in TNF-α mRNA-expression compared to the infection of immune cells (hMdM)." (PMID 32316261, 2020). "In line with this study, real-world data gathered in Japan suggest that the risk for development of TB during treatment with tocilizumab is comparable to the infection risk during TNF antagonist therapy." (PMID 33334075, 2020). "Infection of various human and mouse cell lines with T. gondii prevents apoptosis, caused by different stimuli, such as Fas-dependent cytotoxicity, TNF-α treatment, actinomycin D, growth factor deprivation, and ultraviolet irradiation." (PMID 33013270, 2020). "The critical TNF-α role in connecting the immune cells monocytes, neutrophils, B cell, and T cell function when blocked, has been associated with various infections." (PMID 33209528, 2020). "We found that cDC2s, and at later time points also moDCs, secrete similar levels of IL-1β, IL-8, and TNFα upon infection with the wt and the CagPAI-deficient strain." (PMID 32486097, 2020). "For instance, elevated expression of the inflammatory cytokine tumor necrosis factor (TNF) in the amniotic fluid was associated with both infection and preterm birth." (PMID 32256497, 2020). "Immunological investigation of the ZF strain exhibits susceptibility to infection, T-lymphocytopenia, production of immunoglobulins and nitric oxide, and increased expression of tumor necrosis factor-α (TNF-α) and interleukin-1 beta (IL-1β)." (PMID 33287318, 2020).
infection (continued). "Although it appears that, in contrast to inhibition of TNF, blockade of mIL-6Rα does not account for TB progression in mice, human studies indicate that treatment with tocilizumab increases the risk of serious infections to a similar extent as TNF antagonists." (PMID 33334075, 2020). "Here, they used three well known sera biomarkers such as C-reactive protein, TNF-α, and IgG to monitor possible infection and inflammatory processes associated with two dissolving MNA treatment regimens, using an in vivo model." (PMID 32575392, 2020). "Peritoneal macrophages obtained of NI ccl3+/+ mice were susceptible to in vitro infection by trypomastigote forms of the Colombian strain, which triggered the production of NOx, TNF and IL-10." (PMID 32194558, 2020). "Secondary outcomes included rate and type of infection; cause of mortality; levels of aspartate aminotransferase, alanine aminotransferase, bilirubin and tumor necrosis factor-α; and Maddrey discriminant function." (PMID 31516791, 2019). "Overall, patients with RA who are treated with anti-TNF therapies are at an increased risk for infections and serious infections, including opportunistic infections, and screening for tuberculosis is recommended as described in the prescribing information." (PMID 31429794, 2019). "Adult population studies showed an increased rate of serious infections associated with TNF-alpha inhibitors." (PMID 30658717, 2019). "Infection with influenza A (H1N1) virus was associated more with the following genotypes: TNF-308 AA (OR = 4.041; 95% CI = 1.215–13.4) and IL8 AA (OR = 3.273; 95% CI = 1.372–7.805)." (PMID 32219005, 2019). "The infection model used and the TNF targeting method and efficiency are factors causing varied results." (PMID 30837977, 2019). "OR > 1 indicates the elevated risk of infection in the TNF-alpha inhibitor group compared to the control group." (PMID 30658717, 2019). "TNF-α hyperproduction during infection and malignancy causes adipose tissue cachexia unraveling its important role in modulation of adipose tissue plasticity." (PMID 31453381, 2019). "Eight of the 12 physicians stated that they were aware of vaccination guidelines and seven viewed pre–Anti-TNF therapy vaccination as essential because of the high infection risk and claimed to incorporate it in their daily practice." (PMID 31584996, 2019). "The inflammatory cytokine TNFα which is induced by infection (e.g. with pathogenic Salmonella) induces expression of all complement related genes except C5, C8GH and CR2." (PMID 31888466, 2019). "Systemic immunosuppression associated with anti-TNFα therapies is widely believed to be a confounding factor in infection and HBV reactivation development." (PMID 31194726, 2019). "The results of various studies on the effect of single nucleotide polymorphisms (SNPs) in the promoter region of tumor necrosis factor α (TNFα) gene on susceptibility to infection are controversial." (PMID 31143118, 2019). "For example, upon pathogenic infection, but prior to tumor necrosis factor-α (TNF-α) production, WRS is rapidly secreted from monocytes without de novo synthesis, although the mechanism of secretion is not completely known." (PMID 30613102, 2019). "Recently, SLY was demonstrated to be the main stimulus for TNF-α production independently of its membrane perforation ability, and it was also involved in the invasive infection caused by S. suis." (PMID 31170267, 2019). "Different meta-analyses and national registries have confirmed the increase on the impact of any infections (20%), serious infections (40%), and TB (250%), associated with anti-TNF-α use." (PMID 31134083, 2019). "We conducted a meta-analysis on associations between the TNF-α-308 polymorphism and post-operative infection and report an OR of 1.18 (CI 0.27–5.21)." (PMID 31270721, 2019). "According to the published data, TNF-α blockers based therapy seems to be associated with a higher risk of infections, at times with a worse outcome." (PMID 31469834, 2019).
infection (continued). "A large study in 190,694 adults with IBD did confirm that combination therapy was associated with increased risks of serious infection (HR 1.23; 95% CI 1.05–1.45) compared to anti-TNF monotherapy." (PMID 31126015, 2019). "No significant regulation of genes encoding IL-17/C2, IL-17A/F2, and TNFα was observed for any of the tissues during the infection." (PMID 31220151, 2019). "Among the 12 physicians, 8 stated that they were aware of the vaccination guidelines, and seven viewed vaccination before Anti-TNF therapy as an essential step for the high risk of infection." (PMID 31584996, 2019). "Our group has recently established that in vitro infection of macrophages with MAP caused more production of pro-inflammatory cytokines such as TNFα, IL-6, and IL-12." (PMID 31817071, 2019). "TNF-α which has been produced by leucocytes and endothelial cells is involved in the infection caused by bacteria, viruses, and parasites." (PMID 31192265, 2019). "TNF encodes for TNF-α a pro-inflammatory cytokine involved in acute phase of infection and produced by gingival epithelial cells in response to bacterial stimulation." (PMID 31673005, 2019). "In these studies, authors were mainly engaged in either, identifying a pattern of epigenetic signatures during the infection, or searching evidence for the activation of genes that encode cytokines and the innate immune system, such as TNF-alpha." (PMID 31214179, 2019). "The use of Anti-TNF therapy poses an infection risk to patients and vaccination is required before initiating the therapy; nevertheless, the vaccination rate remains low." (PMID 31584996, 2019). "This meta-analysis investigated prospective trials comparing infection risk in JIA children treated with TNF-alpha inhibitor, in contrast with JIA children receiving DMARD therapy, or placebo in certain publications." (PMID 30658717, 2019). "The present results indicated that the TNF-308 A allele and A/A genotype were associated with a higher risk of infection by influenza A/H1N1, while the homozygous TNF-308G/G genotype had a trend toward being associated with protection from infection." (PMID 32219005, 2019). "In the liver, however, only WT strain infection was associated with elevated TNF-α concentrations (p < 0.01)." (PMID 31131028, 2019). "The use of anti-TNF therapy has been associated with an increased risk of infection and an increased risk of some malignancies compared with the general population." (PMID 31429794, 2019). "The authors noted that this was associated with enhanced TNF-α-induced permeability of the endothelial cells during early infection, decreasing the barrier integrity of the cells, but the barrier integrity was normalized by late-stage infection." (PMID 31783527, 2019). "Previous data have suggested that the risk for infection with TNF inhibitors is highest within the first 90 days of therapy, but to our knowledge, no data are currently available concerning use of IL inhibitors." (PMID 31626313, 2019). "It was found that two principal cytokines, interleukin (IL)-6 and tumor necrosis factor alpha (TNFα), significantly exacerbate inflammation caused by C. difficile in accordance with infection severity." (PMID 31658740, 2019). "TNFα was at higher levels (P < 0.05) in the blood of susceptible lambs, at day 0 of the third artificial infection." (PMID 31815153, 2019). "TNF-308 polymorphisms have been shown to be key acute-phase cytokine polymorphisms that are involved in inflammation in several infections." (PMID 32219005, 2019). "Our observations are consistent with data from mice, in which TNF-α deficiency at the time of infection causes suboptimal activation of dendritic cells and is associated with failure to clear infection." (PMID 30169607, 2019). "In this retrospective cohort study of patients previously treated with methotrexate, we evaluated the effectiveness and risk of serious infection of tofacitinib compared with DMARDs, TNFi, and non-TNF biologics." (PMID 29566769, 2018).
infection (continued). "In mice with T cells deficient in the regulatory cytokine IL-10 (IL-10 KO), infection with Plasmodium chabaudi leads to a hyper-inflammatory response and lethal outcome that can be prevented by anti-TNF treatment." (PMID 29866139, 2018). "Dengue infection caused suppression of TNF-α-mediated hyperpermeability in human umbilical vein endothelial cell (HUVEC) monolayer within 72 h after infection." (PMID 29419739, 2018). "Both TNFα and IL-8 have both been found to be important for control of infection by MABS rough variants in the zebrafish model of infection." (PMID 30443245, 2018). "At 4 hours post-infection, all recombinant C. crescentus tested, including Cc-Control, caused a significant increase in the amount of TNF present in the vaginal lavage when given at the same time as HSV-2." (PMID 29434285, 2018). "The key role of TNF is further reinforced by the finding that patients receiving TNF inhibitor treatment for chronic inflammatory conditions are more susceptible to infection with intracellular bacteria, including Lm." (PMID 29438281, 2018). "The increase in immune cytokines (IL-12p70, IL-4, IL-5, and IL-17A) induced by SPY1 were further upregulated by P17 treatment, whereas the decrease in the infection-associated inflammatory cytokine TNF-α by SPY1 was reversed." (PMID 30116243, 2018). "Subjects with all genotypes of TNF-α (GG, GA, AA) and high infection intensity were significantly related to an increased risk of ICC (p < 0.05)." (PMID 30139338, 2018). "Infection with the LPS-deficient strain resulted in lower serum levels of pro-inflammatory cytokines TNF-α and IL-6 compared to the parent strain, and was less virulent in a mouse model of disseminated sepsis." (PMID 29638177, 2018). "EV71 infection induces high levels of inflammatory cytokines in host cells such as IL-6, IL-10 and TNF-α, with a cytokine storm recognized as the main cause of severe cardiopulmonary manifestations during this infection." (PMID 30545363, 2018). "Given that CF patients with both active and past infection exhibit this TNFα deficiency in response to mitogen, it is more likely that this phenotype is an underlying predisposition to disease rather than a direct effect of the disease." (PMID 29942313, 2018). "Our adjusted comparisons did not demonstrate that tofacitinib users had an increased risk of serious (hospitalized) infections compared with those treated with non-TNF biologics." (PMID 29566769, 2018). "Under pro-inflammatory conditions such as maternal illness or infection, TNF-α signaling in the placenta via TNF receptor 1 is associated with fetal hypoxia and neuroproliferative defects in the fetal brain." (PMID 30200631, 2018). "In an Mtb infection model, TNF-α depletion resulted in increased susceptibility, with mice succumbing to infection within 2–3 weeks, while harboring a high bacterial burden." (PMID 30283449, 2018). "Cytoskeletal rearrangements in epithelial and subepithelial cells are induced by proinflammatory cytokines TNF-α and IL-6, that are known to be up-regulated during infection caused by M. hyopneumoniae." (PMID 30523267, 2018). "Symptomatology induced by hMPV-infection is caused by a typical Th17-like immune response, characterized by the secretion of interleukin (IL)-6 and TNF-α in the lungs." (PMID 30405642, 2018). "Past research suggests that pro-inflammatory cytokines IL-1β and TNF-α play a primary role in inducing infection-associated PTB." (PMID 29867970, 2018). "Noteworthy to conclude, patients that use anti-TNF medication for chronic inflammatory disease are already at higher risk for infections and malignancies for several disease-related reasons, regardless of their treatment." (PMID 29751683, 2018). "In these groups, sex-associated dimorphism was detected depending on the infection status; TNF-α expression was decreased in females and increased in males (P < 0.001)." (PMID 30515051, 2018).
infection (continued). "To enumerate the mechanism that reduces CD169+ cells in TNF-deficient mice after infection, we made use of terminal deoxynucleotidyltransferase-mediated dUTP-biotin nick end labeling (TUNEL) assays." (PMID 29142134, 2018). "Recently, a meta-analysis investigated the infection risk in 53 post-LT patients on anti-TNF-α medications compared with 23 post-LT subjects and 41 PSC-IBD not treated with anti-TNF-α." (PMID 30060508, 2018). "IE1, a promiscuous transactivator of NFκB pathway constituents and their downstream targets during infection, has been implicated in the upregulation of p65, IL-6, TNF-α and IL-8 as well as the induction of p52/RelB heterodimer binding activity in the nucleus." (PMID 30134546, 2018). "Anti-TNF therapy has improved the treatment of inflammatory disease but can predispose to infection and malignancy." (PMID 29636466, 2018). "Participants with TNF-α in all genotypes (GG, GA, AA) who had high infection intensity (IgG antibody > 0.24) had an increased risk of ICC and were statistically significant (OR 2.1 for GG wild-type, OR 2.4 for GA heterozygote and OR 2.8 for AA variant)." (PMID 30139338, 2018). "L-GSH treatment caused a significant decrease in the levels of TNF-α levels in M. tb-infected granulomas from healthy subjects at eight days post-infection." (PMID 29494546, 2018). "Susceptibility to infection is a significant concern following instigation of treatment with anti-TNF." (PMID 30065229, 2018). "In immunized mice, increase in immune cytokines (IL-12p70, IL-4, IL-5, and IL-17A) induced by SPY1 were further upregulated by P17 treatment, whereas the decrease in the infection-associated inflammatory cytokine TNF-α by SPY1 was reversed." (PMID 30116243, 2018). "These unwanted effects are considered as a class effect, because all anti-TNF drugs appear to have an equally high risk in acquiring new tuberculosis infections, although the mAbs seem to cause more infections with reactive latent tuberculosis." (PMID 29751683, 2018). "Immune challenge of invading macrophages at sites of infection is associated with release of TNF, which triggers a local cytokine storm as part of the normal inflammatory response." (PMID 30451876, 2018). "A neutralizing antibody titer was achieved later in TNF-deficient mice than in WT mice after infection with low doses of VSV." (PMID 29142134, 2018). "Cytokines IFN-γ and TNF-α contribute to infection-associated inflammatory complications; however, they also help in elimination of protozoan pathogens with the help of Nitric oxide (NO) produced during infection." (PMID 30619263, 2018). "The protective role of TNF is observed during infection by low pathogenic IAV, where extrinsically derived TNF is responsible for attenuating tissue-damaging CD8+ T-cell response." (PMID 30042762, 2018). "Using 2006–2011 data from the same registry, they also showed that the risk of serious infection was comparable between RA patients receiving tocilizumab and those treated with anti-TNFα agents." (PMID 28594905, 2017). "Although some studies concluded an increased risk of infection in patients receiving infliximab, the relative risk for patients receiving TNF-α inhibitors was reported to be up to twice that of control, and even higher at the treatment’s onset." (PMID 28179019, 2017). "As a result, iRhom2-deficient mice have substantially reduced serum levels of TNFα upon inflammatory challenge with bacterial lipopolysaccharide and consequently reduced survival upon infection with the intracellular bacterium Listeria monocytogenes." (PMID 27256961, 2017). "In healthy individuals, the increased killing was associated with elevated production of IFN-γ, TNF-α and IL-6 in the presence of anti-IL-10 mAb only 6 hours after infection (p < 0.05, <0.001, <0.01 respectively)." (PMID 28216665, 2017).